U3 (Small nucleolar RNA U3 )
Synonyms: LOC124903435
Gene: Small nucleolar RNA gene on chromosome 14 (101,145,480 to 101,145,695, reverse strand). Ensembl gene ENSG00000277754.
Gene Ontology:
Biological process: RNA processing
Cellular component: nucleolus
Homologues: Orthologues: chimpanzee U3 (99% identical), macaque U3 (96% identical). Paralogues in human: U3 (90% identical), SNORD3P1 (84% identical), U3 (82% identical), U3 (81% identical), SNORD3G (80% identical), U3 (80% identical), U3 (79% identical), U3 (78% identical), SNORD3E (77% identical), SNORD3H (77% identical), U3 (77% identical), SNORD3D (76% identical), and 11 more.